PLEKHN1 (pleckstrin homology domain containing N1)
Description:
Controls the stability of the leptin mRNA harboring an AU-rich element (ARE) in its 3' UTR, in cooperation with the RNA stabilizer ELAVL1. Decreases the stability of the leptin mRNA by antagonizing the function of ELAVL1 by inducing its atypical recruitment from the nucleus to the cytosol (By similarity). Binds to cardiolipin (CL), phosphatidic acid (PA), phosphatidylinositol 4-phosphate (PtdIns(4)P) and phosphatidylserine (PS). Promotes apoptosis by enhancing BAX-BAK hetero-oligomerization via interaction with BID in colon cancer cells (By similarity).
Synonyms: CLPABP; DKFZP434H2010
Tractability: Antibody: UniProt places it where antibodies can reach, with high confidence; its Gene Ontology location is reachable by antibodies, with high confidence; the Human Protein Atlas places it where antibodies can reach.
Gene: Protein-coding gene on chromosome 1 (966,437 to 975,865, forward strand). Ensembl gene ENSG00000187583.
Subcellular location: Cell membrane; Mitochondrion; Mitochondrion membrane
Subcellular location (Human Protein Atlas): Plasma membrane; Cytosol
Gene Ontology:
Molecular function: cardiolipin binding; phosphatidic acid binding; phosphatidylinositol phosphate binding; phosphatidylserine binding; protein binding
Biological process: 3'-UTR-mediated mRNA destabilization; positive regulation of apoptotic process; response to hypoxia
Cellular component: cytoskeleton; mitochondrial membrane; mitochondrion; plasma membrane
Genetic constraint (gnomAD): Loss-of-function variants: 69 observed, 62.96 expected, observed/expected ratio (o/e) 1.1, 90% interval 0.9 to 1.34. The synonymous counts are far from expectation, so gnomAD's model fits this gene poorly and the ratio says little. Missense variants: 1,015 observed, 775.65 expected, observed/expected ratio (o/e) 1.31, 90% interval 1.24 to 1.38. Synonymous variants: 454 observed, 340.08 expected, observed/expected ratio (o/e) 1.34, 90% interval 1.24 to 1.44.
Homologues: Orthologues: chimpanzee PLEKHN1 (98% identical), macaque PLEKHN1 (92% identical), pig PLEKHN1 (73% identical), dog PLEKHN1 (69% identical), rat Plekhn1 (68% identical), mouse Plekhn1 (67% identical), guinea pig PLEKHN1 (64% identical). Paralogues in human: MCF2L (16% identical), PLEKHG4B (15% identical), TRIO (15% identical), VAV1 (14% identical), MCF2 (14% identical), VAV2 (13% identical), PLEKHG4 (13% identical), VAV3 (13% identical), ARHGEF40 (13% identical), TIAM1 (13% identical), TIAM2 (13% identical), KALRN (13% identical), and 10 more.
Diseases named in the same sentence as PLEKHN1 in open-access papers:
PLEKHN1 is named in the same sentence as 7 diseases in open-access papers, as found by Europe PMC text mining. Sharing a sentence is not in itself a finding about the gene and the disease. The quoted sentences say what the papers report.
colon cancer (1 paper, 2018). "In particular, digestive organ cancer cell lines, such as 58As9 (scirrhous cancer), CaCO2 and HT-29 (colon cancer) expressed the full-length PLEKHN1, and we could ignore the non-specific band by comparison of PLEKHN1-knockout-HT-29 (hereafter, PLEK-KO cells) and the parental HT-29 cells." (PMID 29531808, 2018).
colorectal cancer (1 paper, 2018). A primary or metastatic malignant neoplasm that affects the colon or rectum. "Loss-of-PLEKHN1 probably causes severe phenotypes in tumor, however, the endogenous colorectal expressions of PLEKHN1 were not high, this could be involved in the general drug resistance of colorectal cancer." (PMID 29531808, 2018).
renal carcinoma (1 paper, 2025). A carcinoma arising from the epithelium of the renal parenchyma or the renal pelvis. "Nine intersecting genes were screened and used to construct a prognostic model, whereby seven key biomarkers—MXD3, PLCB2, CCDC88B, DEF6, IFNG, TBC1D10C, and PLEKHN1—were significantly influenced the prognosis of renal cancer." (PMID 41357186, 2025).
stomach cancer (1 paper, 2018). "Therefore, to examine if the cancerous cells show the lower expression level of PLEKHN1 than that of the surrounding normal tissues, we performed IHC of randomly picked stomach cancer patient specimens with anti-PLEKHN1 antibody." (PMID 29531808, 2018).
tumor (4 papers, 2014 to 2021). "PLEKHN1-deficient cells may survive in large tumor, then, how about cell survival in unstable scaffold such as in body cavity?" (PMID 29531808, 2018). "To test the effects of PLEKHN1-knockout on in vivo tumor outgrowth, we performed subcutaneous injections of cells." (PMID 29531808, 2018).
cancer (2 papers, 2018 to 2024). A tumor composed of atypical neoplastic, often pleomorphic cells that invade other tissues. "As a consequence, they were able to observe an increased in vivo survival rate of cancer cells in PLEKHN1 knock-out mice." (PMID 38840260, 2024). "Despite the expression of PLEKHN1 was induced by stresses, PLEKHN1-knockout increased the cancer cell survival in vivo, thus, PLEKHN1 is prepared for selection of the cells having some damages." (PMID 29531808, 2018). "Human PLEKHN1 was expressed in several cancer cell lines of differing origin." (PMID 29531808, 2018). "Collectively, the silencing of PLEKHN1 may be the key that cancer cells acquire the drug resistance." (PMID 29531808, 2018). "The immunohistochemistry of cancer patient specimens showed that PLEKHN1 expression was absent from cancer region at the transition area of normal/cancer tissues." (PMID 29531808, 2018).
PLEKHN1 also shares sentences with these, for which no sentence is quoted: pancreatic cancer (1 paper).